BACH2 (BACH transcriptional regulator 2)
Diseases named in the same sentence as BACH2 in open-access papers (continued):
Sharing a sentence is not in itself a finding about the gene and the disease.
tumor (continued). "However, cellular senescence and apoptosis are two types of cellular responses to DNA and cellular damage that are altered in both cancer (BACH2 repression in CD4+ T cells modulates their resistance to apoptosis demonstrating it functions as a tumor suppressor gene, in preparation) and aging." (PMID 30654767, 2019). "Thus, the alternative Bach2 promoter was highly activated in tumor 1206." (PMID 19159451, 2009). "It is therefore plausible that ho22R triggers BACH2 expression to endow CD8+ T cells with stem-like properties and enhanced anti-tumour capacity, although the exact molecular cascades remain to be elucidated." (PMID 40804519, 2025). "Since BACH2 plays a tumor-suppressor role in MCL and decreased BACH2 levels lead to BTZ resistance, we first determined the BACH2 levels in one BTZ-sensitive cell line Jeko and one BTZ-resistant MCL cell line REC-1." (PMID 34039348, 2021). "Compared to the control group, the sh‐BACH2, sh‐FUS, TSLNC8‐OE and sh‐BACH2+sh‐FUS+TSLNC8‐OE groups produced smaller tumour volumes." (PMID 32892482, 2020). "These target genes are known to participate in tumor progression, but the suggested regulatory roles of PAX4, BACH1, BACH2, MAZ and TAF8 in the process is new." (PMID 21682879, 2011). "While conventional high-level overexpression of BACH2 enforces quiescence and hinders tumor control, low-dose BACH2 expression promotes persistence without compromising effector function, enhancing anticancer efficacy." (PMID 41545541, 2026). "Moreover, the phenotypes induced by BACH2 overexpression in T-ALL cells can be reversed by reduction in BACH2 levels, further supporting a tumor-suppressor-like role of BACH2 in T-ALL cells." (PMID 38233409, 2024). "Since Bach2-deficient NK cells showed skewed differentiation with increased expression of effector molecules, especially cytotoxic genes and increased cell numbers in lung, we evaluated whether mice lacking Bach2 in NK cells would result in better control of tumor lung metastases in vivo." (PMID 36190189, 2022). "Along with this, NK cells lacking Bach2 expression were more terminally differentiated and demonstrated better control of tumor metastasis." (PMID 36190189, 2022). "Lack of BTB domain And CNC Homolog 2 (Bach2) expression in natural killer (NK) cells suppresses B16F10 tumor metastasis." (PMID 36190189, 2022). "Furthermore, NAC-treated tumor-infiltrating wild-type Treg cells exhibited increased IFN-γ production, as well as SUMOylation of BACH2." (PMID 30089837, 2018). "We have not been able to detect Bach2 mRNA containing exon 5A in any tumor samples except 1206, or in normal spleen tissue (data not shown)." (PMID 19159451, 2009). "The existence of Bach2 mRNAs containing exon 5A was verified by RT-PCR and sequencing of tumor material from mouse 1206 (data not shown)." (PMID 19159451, 2009). "Indeed, we and others have revealed a tumor-suppressor role of BACH2 in B-cell leukemias and non-Hodgkin’s lymphomas (NHLs)." (PMID 38233409, 2024). "NK cell-mediated control of tumor metastasis was also augmented in the absence of Bach2." (PMID 36190189, 2022). "Thus, the promoter sequence in front of exon 2A seems not to be the target for the observed Bach2 deregulation in tumor 1206." (PMID 19159451, 2009). "Given that only a minor fraction of the tumor cells harbours the proviral integration, it may not be surprising that in most cases we were unable to detect Bach2 transcriptional deregulation." (PMID 19159451, 2009). "The existence of Bach2 mRNAs including exon 5B (the second exon of EST AK162095) was verified by RT-PCR and sequencing of tumor material from mouse 1206 (data not shown)." (PMID 19159451, 2009).
cancer (42 papers, 2016 to 2026). A tumor composed of atypical neoplastic, often pleomorphic cells that invade other tissues. "Dysregulation of the Menin-Bach2 pathway may contribute to the pathogenesis of HTLV-1 associated cancer and inflammatory diseases via mechanisms mediated by Tax and/or HBZ." (PMID 40128849, 2025). "Thus, the Menin-Bach2 pathway is important for age-related immune dysfunction and susceptibility to chronic inflammation and cancer." (PMID 40128849, 2025). "Defective provirus integrations are enriched in proximity to some cancer-associated genes such as BACH2, MKL2, and STAT5B, but whether integration in the proximity of such genes favors clonal expansion remains to be determined." (PMID 34636876, 2021). "However, in some cancers it was mutated or fused with other genes leading to dysregulated expression of BACH2 itself or BACH2 fusion protein." (PMID 30459773, 2018). "Therefore, rather than preferential integration into these genes during acute infection, the enrichment into certain cancer-related genes such as BACH2 is more likely caused by the survival benefit and preferential proliferation of these cells after long-term infection." (PMID 34578439, 2021). "To understand the dynamics of exhausted T cells, we examined the relationship between the expression of the stem-like markers Tcf7, Slamf6, Lef1, and Bach2 and the exhaustion markers across the pan-cancer dataset." (PMID 40076932, 2025). "Overexpression of BACH2 in T-ALL cells not only induced cell growth retardation but also inhibited cancer progression and infiltration in xenografts." (PMID 38233409, 2024). "Another study revealed that BACH2 inhibits NK maturation and cell function in mice and humans, limiting the cytotoxic response to cancer." (PMID 38891024, 2024). "Third, evening chronotype has been associated with DNA methylation of certain gene sites, like BACH2, JRK and RPS6KA2, which are related to the cancer development." (PMID 36093575, 2023). "Although BACH2 has been reported to affect CP, IBD, and cancer by regulating adaptive immunity, the specific functions of BACH2 are unclear." (PMID 37228820, 2023). "BACH2, an active marker gene of B cells, has hypermethylated DMRs consisting of 11 CpGs on the second intron out of six introns in tumors (benign and carcinoma)." (PMID 37460953, 2023). "Previous studies have shown an enrichment of IS in cancer-associated genes, such as STAT5B and BACH2, suggesting IS-driven expansion of infected cells." (PMID 34140517, 2021). "The HIV-1 integration site patterns are similar to those observed in adults, including enrichment of integration into cancer-related genes BACH2 and STAT5B with the same orientation to the transcription units." (PMID 34578439, 2021). "Among the SNV top-ranked promoters (DMD), DHS elements (LRMP) and enhancers (PAX5, BACH2, BCL2, CXCR4, and BCL7A) are highly cancer-type-specific cases with many BCL or CLL mutations." (PMID 29354286, 2018). "Normal HIV integrations into the oncogenes BACH2 and MKL2 can cause the clonal expansion and proliferation of the infected cells, and rearrangements of BACH2 and MKL2 can cause cancer in humans." (PMID 27682062, 2016). "However, in the context of chronic disease such as cancer, BACH2 has been shown to drive Treg cell quiescence and maintenance of immune homeostasis." (PMID 40461772, 2025). "In addition, the decreased BACH2 levels in T-ALL cells also promote cancer development by de-repressing other key effectors." (PMID 38233409, 2024). "It has been discovered that Bach2 is required for immunosuppression in cancers." (PMID 38459508, 2024). "The targeted DMR of BACH2 was the most hypermethylated in benign, followed by carcinoma." (PMID 37460953, 2023). "As a result, our study suggests that Bach2 may be a novel target for checkpoint inhibition of NK cells for cancer immunotherapy." (PMID 36190189, 2022).
cancer (continued). "For example, dCas9-Dnmt3a-based system has been used to increase DNA methylation for repressing the transcription of oncogenes CDKN2A (cyclin-dependent kinase inhibitor 2A) and BACH2 (BTB domain and CNC homolog 2) in cancer development associated with aberrant DNA methylation." (PMID 36109806, 2022). "Furthermore, HIV-1 integration into cancer-related genes such as BACH2 and MKL2 was identified during acute infection." (PMID 34578439, 2021). "However, analysing the distributions of the expression of BACH2 in cancer vs. normal tissue we see a small but significant difference." (PMID 33806327, 2021). "A recent study reported that BACH2 promoted immunosuppression in cancer." (PMID 32101536, 2020). "If HIV-1 provirus happens to integrate into cancer-related genes, such as BACH2 and MKL2, the infected cells may undergo aberrant proliferation." (PMID 31910871, 2020). "However, the role of BACH2 in tumorigenesis remains controversial and alters as per tissue and cancer type." (PMID 33316777, 2020). "Notably, genes associated with these conversions, like BCL6 and BACH2, are downregulated more swiftly than others when subjected to JQ1, a super-enhancer-disrupting bromodomain and extra-terminal domain inhibitor utilized in cancer chemotherapy." (PMID 40631184, 2025). "Most notably, the study’s main finding, an association between a genetic variant in BACH2 and the cisplatin-induced decrease in eGFR in adult cancer cohorts, was not present in this study’s cohort, although the direction of the effect was the same in both studies." (PMID 35743677, 2022). "Thus, BACH2-KRAS offers a potential target for treatment of cancer by reversing immunosuppression." (PMID 32101536, 2020). "Genes like BCL6 and BACH2 tied to these conversions are downregulated faster by JQ1, a super-enhancer-disrupting anti-cancer agent." (PMID 40998810, 2025). "A similar analysis was performed at the mRNA level, revealing BACH2 (9 tissue-specific interactions in COAD) and SLC2A1 and TBL1XR1 (7 interactions in different cancer tissues) as the most recurrent mRNAs." (PMID 41183125, 2025). "Direct comparison of FPKM distributions show us that all three transcription factors: BACH2, MAFK and NFE2L2 are downregulated in cancer cells." (PMID 33806327, 2021). "As recent review reported several pathways in Treg from cancers including Foxp3, IRF4, PI3/AKT/FoxO axis, Helios, Eos, Nr4a, Bach2, E proteins and their inhibitor of DNA-binding (Id) counterparts, STAT3, and NF-kB." (PMID 34084175, 2021). "In the context of cancer, BACH2 exerts its regulatory influence on TCR-induced transcriptional changes, particularly those crucial for maintaining Treg quiescence and homeostasis, mechanisms involved in cancer immunosuppression." (PMID 38891024, 2024). "Regarding DNA methylation, it is worth noting that the promoter regions of BACH2, MTAP, and RUNX1T1 were hypermethylated in NII.clusterB-PNI patients compared with NII.clusterA-PNI patients.These genes act as inhibitory factors in cancer." (PMID 37563649, 2023). "During acute infections HIV-1 integration into certain cancer-related genes such as BACH2 is observed; however, it is not enriched." (PMID 34578439, 2021). "DNA rearrangements in both BACH2 and MKL2 are known to play a role in human cancers." (PMID 27682062, 2016).
infection (19 papers, 2010 to 2026). The state of being infected such as from the introduction of a foreign agent such as serum, vaccine, antigenic substance or organism. "Conversely, Bach2, which encodes a basic region-leucine zipper (bZip) transcription factor (TF) that prevents plasma cell formation from naïve B cells by inhibiting the expression of Blimp151, was found to be significantly upregulated in young plasma cells on day 3 post-infection." (PMID 37852965, 2023). "Infection of CD4+ T cells using lentivirus harboring sh-NR4A1 revealed that NR4A1 silencing caused the NR4A1 and BACH2 downregulation in the presence of modeling and daphnetin treatments." (PMID 41462398, 2025). "One resounding theme across in vitro infection, untreated and treated in vivo infection was heightened accessibility for AP-1 family (Fos, Jun) and Bach1/Bach2 transcription factor motifs." (PMID 36536105, 2023). "This includes BACH2 (individual 3, time point 1 collected approximately 2.3 months after estimated date of infection)." (PMID 33784259, 2021). "This latter result was surprising given the increased expansion of Th1 and Tr1 cells in P. chabaudi-infected B6.Bach2ΔT mice, compared to control mice, and indicates both cell extrinsic and intrinsic roles for BACH2 in Tr1 cell expansion during infection." (PMID 30459773, 2018). "BACH2 is repressed upon infection of naïve B cells, and is derepressed in 3AmutB (but not 3BKO) LCLs." (PMID 21085583, 2010). "In addition, BACH2 seems to play an intrinsic role in T lymphocytes, being related to the expansion and/or survival of T lymphocytes during infection by Plasmodium chabaudi and Leishmania (Leishmania) donovani." (PMID 37376405, 2023). "BACH2 has also been shown to promote Th1 cell responses over Th2 cell responses during infection." (PMID 30459773, 2018). "Since BACH2 influenced effector CD4+ T cell subset development in vitro, and in particular the development of Tr1 cells, we hypothesized that BACH2 would influence cellular responses during infection, and consequently, affect disease outcome." (PMID 30459773, 2018). "Thus, Bach2 regulation of Tregs depends on the infection type." (PMID 36033397, 2022). "Also, given the down-regulation of Bach2, it may be informative to examine the impact of Bach2 over-expression during infection in future studies." (PMID 30459773, 2018). "For example, the expression of many TFs changed significantly over the course of infection, including decreases in Fos, Jun, and BCL6, and increases in Bach2 and BATF." (PMID 33497421, 2021). "We showed that T cell-specific BACH2 modulates Th2 and Th17 cell differentiation, and suppressed effector CD4+ T cell responses during infection." (PMID 30459773, 2018). "However, the possibility that downregulation of BACH2 may be a result of infection could not be excluded." (PMID 41614877, 2025). "Therefore, although BACH2 may interact with BLIMP1 to influence CD4+ T cell development and differentiation, our results indicate that this interaction plays a limited role in determining the outcome of infection with P. chabaudi or L. donovani." (PMID 30459773, 2018). "During the transition from naive CD4+ T cells to TfhD3 under HIVYu2b infection, we observed no downregulation of PRDK2 and BACH2, two inhibitors of the Tfh cell program." (PMID 34984326, 2022). "The expression of BACH2 and BCL6 was not changed or was only marginally affected in SKW6.4 cells transduced with lentiviral vectors expressing miR-34a-5p, -148a-3p, or -183-5p at a low multiplicity of infection (moi)." (PMID 26655851, 2015).
cardiovascular disease (3 papers, 2022 to 2025). "In cardiovascular disease and other immuno-inflammatory diseases, the role of BACH2 in regulating immune homeostasis is incompletely understood." (PMID 40461772, 2025). "However, the role of BACH2 in cardiovascular diseases is still unclear." (PMID 36105283, 2022).
inflammation (2 papers, 2016 to 2022). Aberrant reaction of the microcirculation characterized by movement of fluid and leukocytes from the blood into extravascular tissues. "Most strikingly, Treg-specific Bach2 deficiency resulted in enhanced fungal protease-induced Type 2 allergic inflammation in the lungs, with no detectable effects on Type 1 responses to systemic or respiratory viral infections." (PMID 36033397, 2022). "Thus, Bach2 deficiency in Tregs is not sufficient to cause unprovoked TH2-driven lung inflammation." (PMID 36033397, 2022).
neurodegenerative disease (2 papers, 2024 to 2025). A disorder of the central nervous system characterized by gradual and progressive loss of neural tissue and neurologic function. "Additionally, we also observed widespread changes in both the expression and motif activity of BACH2 across all human AD cell types, underscoring the broader relevance of BACH2–mediated regulation in neurodegenerative diseases." (PMID 41015942, 2025). "There are no published studies regarding Bach1 and Bach2’s involvement in mediating ferroptosis in neurodegenerative diseases." (PMID 39040474, 2024).
BACH2 also shares sentences with these, for which no sentence is quoted: Addison’s disease (3 papers); autoimmune thyroid disease (3); type 2 diabetes (3); Chronic Lymphocytic Leukaemia (2); coronavirus disease 2019 (2); nasopharyngeal carcinoma (2); polyendocrinopathy (2); Stroke (2); acute coronary syndrome (1); acute kidney injury (1); adult T-cell leukemia (1); Airway obstruction (1); Allergy (1); autoimmune pancreatitis (1); autoimmune polyglandular syndrome type 1 (1); B-cell neoplasm (1); breast carcinoma (1); childhood asthma (1); chronic granulomatous disease (1); colon cancer (1); digestive system disorder (1); gynecological tumors (1); heart failure (1); hematological malignancies (1); Hyperglycemia (1); intestinal tumors (1); leishmaniasis (1); lipoma (1); liver cancer (1); liver steatosis (1).
A further 19 diseases each share a sentence with BACH2 in 1 paper.